PTX3 (pentraxin 3)
Diseases named in the same sentence as PTX3 in open-access papers (continued):
Sharing a sentence is not in itself a finding about the gene and the disease.
Sepsis (continued). "We acknowledge pivotal discoveries from preceding research and engage in discourse regarding the challenges and limitations confronted by PTX-3 as a sepsis biomarker." (PMID 39021820, 2024). "In conclusion, PTX-3 emerges as a valuable candidate as a biomarker for sepsis, providing insights into its structural characteristics, physiological functions, and potential diagnostic applications." (PMID 39021820, 2024). "Although PTX-3 has good prospects as a biomarker for sepsis, challenges and limitations still need to be addressed." (PMID 39021820, 2024). "PTX3 can attenuate myocardial injury in sepsis due to the down-regulation of apoptosis and autophagy induced by the PI3K/AKT/mTOR pathway." (PMID 38784395, 2024). "Despite emerging evidence indicating that PTX3 is a robust prognostic predictor of sepsis, its role in resistance against bacterial infection remains controversial." (PMID 39666228, 2024). "The purpose of this review is to summarize the current literature on one of the sepsis biomarkers, PTX-3, to provide a comprehensive overview of the research progress on PTX-3 as a sepsis biomarker." (PMID 39021820, 2024). "In a prospective observational analysis, the combined measurement of PTX3, IL-6, PCT, and lactate demonstrated excellent predictive performance for 28-day all-cause mortality in patients with sepsis or septic shock, surpassing the SOFA score." (PMID 39201697, 2024). "This study aimed to investigate the effect and mechanism of Pentraxin 3 (PTX3) on myocardial injury in sepsis." (PMID 38784395, 2024). "In infectious shock, sepsis, and other inflammatory and infectious states, plasma PTX-3 levels increase sharply, reaching a peak level within 6–8 h, and its concentration can increase up to 100 ng/mL during sepsis." (PMID 39021820, 2024). "Our study highlighted the pivotal role of PTX3 in the impact of interactions between cell death of hepatocytes and immune cells activation in sepsis." (PMID 39666228, 2024). "One study showed that when using the PTX-3 cut-off value of 5.6 μg/L to diagnose sepsis, the sensitivity was 98.3%, the specificity was 96.7%, the positive predictive value (PPV) was 98%, and the negative predictive value (NPV) was 96%." (PMID 39021820, 2024). "Similar to adults, PTX-3 can be used as a reliable biomarker for neonatal sepsis with high sensitivity and specificity." (PMID 39021820, 2024). "Of note, one innate immune system protein called pentraxin 3 (PTX3) was recently assessed for its potential as a biomarker for early sepsis." (PMID 38255280, 2024). "Plasma levels of pentraxin-3, monocyte chemoattractant protein 1 and angiopoietin-2 are early biomarkers for assessing the severity of sepsis and septic shock." (PMID 38716051, 2024). "Pentraxin-3 (PTX-3), which plays a crucial role in the early phase of inflammation by activating the complement cascade, was identified as a marker of sepsis severity and exitus." (PMID 37569751, 2023). "In sepsis, available data were mainly obtained in ICU patients and indicated that PTX3 is associated with disease severity, organ dysfunction and 28-days or 90-days mortality." (PMID 36189302, 2022). "In parallel, both PTX3 and sIL-1R2 are increased with the increasing of severity from non-sepsis to sepsis and septic shock." (PMID 36189302, 2022). "Our data indicate that high levels of PTX3 in plasma of patients with suspected sepsis admitted to the emergency room can be used as a prognostic marker for risk stratification." (PMID 36189302, 2022). "The efficacy of PTX3 as a biomarker tool in sepsis has been demonstrated in the work of many studies." (PMID 36168379, 2022). "It is shown that the circulating levels of PTX3 exhibit a gradient from systemic inflammatory response syndrome (SIRS) to sepsis and septic shock in infection." (PMID 35676730, 2022). "The purpose of this study was to clarify the prognostic value of Pentraxin-3 (PTX3) on the mortality of patients with sepsis." (PMID 35676730, 2022).
Sepsis (continued). "PTX-3 levels were elevated at the onset of sepsis and increased with illness severity and the number of organ dysfunctions." (PMID 34991675, 2022). "Our meta-analysis consistently suggested that serum PTX3 level was a useful prognostic biomarker for patients with sepsis." (PMID 35676730, 2022). "Plasma PTX-3 was assessed on days 1, 2, and 7 in 958 patients with sepsis or septic shock included in the Albumin Italian Outcome Sepsis (ALBIOS) study." (PMID 34991675, 2022). "We aimed to provide an updated meta-analysis to further understand the predictive value of PTX3 in sepsis-related mortality." (PMID 35676730, 2022). "In humans, PTX3 levels rise rapidly and dramatically in various pathological conditions of inflammatory or infectious origin, such as endotoxic shock and sepsis." (PMID 35989325, 2022). "This study aims to identify pentraxin 3 (PTX3) as a predictor of sepsis in patients who are critically ill and admitted to intensive care units." (PMID 36168379, 2022). "EtOH feeding to C57BL/6 mice significantly diminished survival rates and lung PTX3 expression in a model of sepsis, and delayed tumor necrosis factor α (TNFα) level increases in plasma." (PMID 35634317, 2022). "In various pathological conditions, ranging from cardiovascular diseases to infections and sepsis, PTX3 plasma levels are increased and generally correlated with severity." (PMID 36389697, 2022). "Second multi-stepwise forward linear regression analysis was done to see better predictors of PTX3, adjunctively demonstrating its correlation with sepsis." (PMID 36168379, 2022). "The optimal cut-off value of serum PTX3 to discriminate sepsis from healthy individuals was 15.10 ng/mL (sensitivity, 92.6%; specificity, 97.4%; P < 0.001) and distinguish septic shock was 58.28 ng/mL (93.2% sensitivity, 60.7% specificity, P < 0.001)." (PMID 33315349, 2021). "Our study also demonstrates associations between markers of the host response to bacterial infection (PCT and PTX-3) and glycemic control in sepsis." (PMID 33755703, 2021). "Our results are consistent with previous studies that confirmed PTX3 as a prognostic biomarker for sepsis." (PMID 34679604, 2021). "Of note, PTX3 has been described by our group and others as a functional player and relevant biomarker in sepsis." (PMID 34248970, 2021). "We have previously shown that multimers of plasma pentraxin-3 (PTX3) were predictive of survival in patients with sepsis." (PMID 33288685, 2021). "The present study shows that Presepsin was, as the case in sepsis, inferior to PTX3 in predicting IVIG resistance and/or CAL formation." (PMID 33912155, 2021). "All of these biomarkers were significantly increased in the sepsis group compared to the healthy group, and PTX-3 had the highest AUC of 0.798 (95% CI 0.666–0.921, p < 0.0001) for predicting septic shock." (PMID 33803628, 2021). "PTX3 plays essential role in innate immunity and Complement activation and its serum level correlates with the severity of sepsis disease." (PMID 33868226, 2021). "PTX-3 can serve as an independent predictor of systemic infections such as sepsis, and PTX-3 levels are rapidly increased in the early stage of pancreatitis." (PMID 34187463, 2021). "A prospective study of 101 patients compared sepsis and healthy groups by measuring plasma PTX-3, MCP-1, and angiopoietin (Ang)-2 levels on the first day of sepsis onset." (PMID 33803628, 2021). "Pentraxin-3 (PTX3) was shown to be associated with the severity and outcome of sepsis and septic shock." (PMID 34679604, 2021). "We next analyzed total peripheral blood leukocytes and, in the context of comparable sepsis-induced leukopenia, neutrophilia appeared already at the early time point after infection in Ptx3-/- mice (P = 0.04)." (PMID 34093560, 2021).
Sepsis (continued). "PTX3 showed relatively better performance (accuracy and stability) for the diagnosis and stratification of sepsis, with the cut-off value of 11.12 ng/mL (p = 0.001, p < 0.001, respectively), although PCT showed larger AUC-ROC instead of better stability." (PMID 34679604, 2021). "Although pentraxin-3 has been well studied in other diseases such as sepsis, acute pancreatitis and dengue hemorrhagic fever, its expression and role has not been reported in HTNV-induced HFRS." (PMID 34001041, 2021). "Consistent with our previous results on PTX3 in sepsis patients, PTX3 also emerged as a strong predictor for mortality in COVID-19 ICU patients." (PMID 34099652, 2021). "PTX3 is correlated with the severity of sepsis in febrile patients presenting with the disease in hospital emergency rooms." (PMID 33912155, 2021). "PTX3 levels are low under normal conditions (<2 ng/ml in adults, 1.24 ng/ml [0.87–2.08] in children), but the plasma PTX3 concentrations increase in certain conditions such as sepsis, small-vessel vasculitis, and acute myocardial infarction." (PMID 33912155, 2021). "Univariate analysis demonstrated that PTX3, PCT, lactate, and platelet count were significantly associated with the diagnosis and severity of sepsis." (PMID 34679604, 2021). "Previous studies have indicated that the levels of pentraxin-3 showed significant correlations with coagulation and inflammation parameters in patients with sepsis, nephropathia epidemica, and other infectious diseases." (PMID 34001041, 2021). "Meanwhile, the expression of PTX3 was strongly correlated with organ dysfunction and the severity of sepsis." (PMID 34679604, 2021). "PTX-3 can serve as an independent predictor of systemic infections such as sepsis, as well as the disease severity." (PMID 34187463, 2021). "The combined biomarker approach using PTX3, PCT, IL6, and lactate showed good performance in predicting 28-day all-cause mortality among the patients diagnosed with sepsis or septic shock as defined by Sepsis-3." (PMID 32481464, 2020). "High PTX3 concentration has been associated with endothelial dysfunction, and increasing data indicate that PTX3 is a prognostic factor for diverse clinical conditions, such as acute and chronic heart diseases, sepsis and pre-eclampsia." (PMID 32372340, 2020). "Our study findings are consistent with previous studies that examined PTX3 as a prognostic marker for sepsis." (PMID 33301518, 2020). "In summary, our results support the available published studies suggesting the prognostic value of a single determination of plasma PTX3 as a predictor of hospital mortality in septic shock patients, defined according to the latest Sepsis-3 criteria." (PMID 33301518, 2020). "Increased circulating levels of PTX3 were observed in sepsis patients, as were the formation of complexes with neutrophil extracellular traps (NETs)." (PMID 33111742, 2020). "In a systematic review and meta-analysis, PTX3 was identified as a marker of sepsis severity and predictor of mortality, but with limited specificity." (PMID 33301518, 2020). "In a systematic review and meta-analysis, PTX3 significantly predicted disease severity and mortality in sepsis." (PMID 33301518, 2020). "Another study showed that PTX-3 discriminates sepsis and septic shock patients from healthy controls in a medical intensive care unit (ICU) setting." (PMID 31243609, 2019). "The results showed that MCP1, PTX3 and Ang2 had higher levels in sepsis patients, especially in those with septic shock, compared with controls." (PMID 31489646, 2019). "In the present study, we evaluated the diagnostic and prognostic values of IL-6, PTX3, PCT, CRP, and lactate in patients with sepsis and septic shock diagnosed using Sepsis-3 definitions." (PMID 31718563, 2019).
Sepsis (continued). "Multivariate logistic regression was performed to model the ability of the biomarker combination (IL-6 and PTX3) to discriminate septic shock patients from sepsis and to predict 28-day mortality among the overall patients." (PMID 31718563, 2019). "The purpose of the present study was to investigate both the diagnostic and prognostic value of IL-6, PTX-3, and PCT among patients with sepsis and septic shock diagnosed at an emergency department (ED) using the latest Sepsis-3 definitions." (PMID 31243609, 2019). "High serum-levels of PTX3 have been linked to the development of systemic inflammatory response syndrome (SIRS) and sepsis, and ultimately fatal outcomes in critically ill patients." (PMID 31798002, 2019). "The present study aimed to investigate both the diagnostic and prognostic values of IL-6, PTX3, and PCT in the emergency department (ED) patients with sepsis and septic shock using the Sepsis-3 definitions." (PMID 31718563, 2019). "PTX3 blood levels can reach 800 ng/ml in patients with endotoxin shock, sepsis and infections of viral, bacterial or fungal origin." (PMID 31057548, 2019). "In a recent study, PTX3 distinguished sepsis and septic shock from controls, which corresponds to uniform cut-off levels in accordance with Sepsis-3 definitions." (PMID 31718563, 2019). "Among 143 enrolled subjects (51 with sepsis, 46 with septic shock, and 46 healthy volunteers), serum levels of IL-6, PTX-3, and PCT were measured." (PMID 31243609, 2019). "In a systematic review and meta-analysis, PTX3 was identified as a marker of sepsis severity and predictor of mortality." (PMID 31718563, 2019). "The induction of PTX3 by primary pro-inflammatory cytokines and microbial components prompted to analyse the circulating levels of this protein in sepsis and its complications." (PMID 31031772, 2019). "The optimal cut-off value to discriminate sepsis from controls was 52.60 pg/mL for IL-6 (sensitivity, 97.0%; specificity, 97.2%; P < 0.001) and 15.10 ng/mL for PTX3 (sensitivity, 92.6%; specificity, 97.4%; P < 0.001)." (PMID 31718563, 2019). "Here, we will present the experimental evidence showing the functional roles of PTX3 and its potential as biomarker focusing on infections and sepsis." (PMID 31031772, 2019). "PTX3 levels were consistently higher in patients with sepsis or septic shock and were predictor of mortality also when evaluated according to the latest Sepsis-3 definition." (PMID 31031772, 2019). "The aim of this study was to investigate the diagnostic value of PTX3, MCP1 and Ang1/Ang2 in patients with sepsis and septic shock on the first day of sepsis onset according to the latest Sepsis 3.0 definitions." (PMID 31489646, 2019). "IL-6 level was superior to PTX-3 and PCT levels in both diagnostic and prognostic value for sepsis and septic shock diagnosed in the emergency department using Sepsis-3 definitions." (PMID 31243609, 2019). "The median value of plasma MCP1, PTX3, Ang1 and Ang2 in septic shock patients was 661.32, 14 635.50, 10 400.00 and 8213.00 pg/mL, respectively, while the median value of MCP1, PTX3 and Ang1 in sepsis group was similar to the post‐surgery group." (PMID 31489646, 2019). "Using APACHE II and SOFA scores as the reference of the severity of sepsis, a significant correlation was identified between the two scores and the concentrations of PTX3, PCT and lactate." (PMID 29435167, 2018). "New pertinent cellular models are required to better understand the contribution of every (blood) cell type to PTX3 expression and the feedback loops with its environment during the host response in sepsis." (PMID 30687307, 2018). "Taken together, these findings confirmed the prognostic value of PTX3 in patients with sepsis/septic shock." (PMID 29435167, 2018). "A review concluded that PTX3 has solid prognostic value in sepsis and correlates with organ dysfunction, but with limited specificity." (PMID 29435167, 2018).
Sepsis (continued). "Although this remains to be demonstrated, the PI3K/Akt pathway described in sepsis represents a potential driver of PTX3 expression in sepsis, as recently demonstrated in cancer and in inflammatory condition." (PMID 30687307, 2018). "Altogether, these observations, which demonstrate the capacity of PTX3 secretion by tolerizable circulating immune mononuclear cells, emphasize the anti-inflammatory role of PTX3 in sepsis." (PMID 30687307, 2018). "This study has some limitations to take into consideration regarding the mechanisms of production and action of PTX3 in sepsis pathophysiology." (PMID 30687307, 2018). "In summary, our study confirmed that PTX3 can be considered as a useful biomarker in prediction severity and outcome of patients with sepsis." (PMID 29435167, 2018). "PTX3 is barely detectable in the plasma of healthy individuals (<2 ng/mL), but its concentration can increase to up to 100 ng/ml during sepsis depending on the severity of disease." (PMID 30687307, 2018). "The study revealed that valuable and consistent discrimination of sepsis and septic shock was achieved by measurements of PTX-3 plasma levels during days 1, 3, and 8 of ICU treatment, specifically for the presence of at least sepsis." (PMID 28793880, 2017). "PTX-3 levels on day one were higher in the sepsis cohort (median 31.4 ng/ml) compared to the SIRS cohort (median 23.8 ng/ml), however not statistically significant (p > 0.05)." (PMID 28793880, 2017). "PTX-3 levels of patients with sepsis or septic shock were consistently significantly higher than in the control group (p ≤ 0.001)." (PMID 28793880, 2017). "In line with previous studies, this study confirms that circulating PTX3 concentrations are elevated in sepsis and even higher in septic shock." (PMID 28793880, 2017). "Recent studies have shown PTX3 levels to be elevated in the presence of a bacterial infection and in a murine sepsis model." (PMID 28458531, 2017). "PTX-3 levels valuably discriminated the presence of at least sepsis on each day (minimal AUC = 0.82) as well as of septic shock (minimal AUC = 0.73) and was overall comparable to IL-6 and PCT." (PMID 28793880, 2017). "In summary, PTX-3 valuably discriminates the different stages of sepsis severity during the first week of intensive care treatment according to latest Sepsis-3 definitions." (PMID 28793880, 2017). "Considering the report that PTX3-transgenic mice are resistant to death from sepsis, the complex formation of PTX3 and histones is considered to have a host-protective in sepsis by attenuating extracellular histone-mediated detrimental effects." (PMID 27656184, 2016). "Extracellular histones were identified in a proteomic analysis of circulating PTX3 complexes in patients with sepsis." (PMID 27656184, 2016). "The PTX3 concentrations determined with the SPR-based immunoassay in the plasma of 21 patients with sepsis, ranging 15–1600 ng/mL, were superimposable to those found in a classic ELISA immunoassay." (PMID 24949642, 2014). "The aim of this systematic review is to provide an overview of studies investigating the diagnostic and prognostic properties of PTX3 in critically ill patients with SIRS, sepsis, or bacteremia." (PMID 25530683, 2014). "Even more dramatic increases in plasma PTX3 (up to 1500 ng/mL) are observed during endotoxic shock, sepsis, and other inflammatory and infectious conditions, including A. fumigatus infection, meningococcal diseases, dengue, tuberculosis, and leptospirosis." (PMID 24949642, 2014). "In the case of sepsis patients, both PTX3 and high PCT seemed to be independent predictors of severe sepsis while CRP did not." (PMID 25530683, 2014). "We reviewed the usefulness of systemic levels of PTX3 in critically ill patients with systemic inflammatory response syndrome (SIRS), sepsis, and bacteremia, focusing on its diagnostic and prognostic value." (PMID 25530683, 2014).